EGFR (epidermal growth factor receptor)
Diseases named in the same sentence as EGFR in open-access papers (continued):
Sharing a sentence is not in itself a finding about the gene and the disease.
tumor (continued). "EGF, on the other hand, plays a role in tumour progression by enhancing cell proliferation, survival, and migration, as it binds to the epidermal growth factor receptor (EGFR)." (PMID 40906384, 2025). "The LUAD_P06T, HCC_P08T, CRC_P09T, GC_P02T, and BC_P02T tumour cell subclusters, on the other hand, were more active in the EGFR, MAPK, NFκB, and TNF-α pathways." (PMID 39877290, 2025). "In patient‐derived models, the pan‐RAS inhibitor RMC‐6236 combined with EGFR inhibitors demonstrated significant synergistic effects and prevented long‐term tumor cell outgrowth." (PMID 40956140, 2025). "Epidermal growth factor receptor (EGFR) has been recognized as a pivotal target in the development of anti-tumor pharmacological agents." (PMID 40864816, 2025). "One tumor showed upregulation at low entinostat concentrations with a subsequently inverse dose-dependence, and in only one tumor EGFR levels remained unchanged." (PMID 39864337, 2025). "The analysis revealed that the age, tumor size, nodal status, and EGFR score significantly influenced both the 5-year DFS and OS (p < 0,05)." (PMID 40150035, 2025). "NSCLC is further classified based on the presence of actionable genetic alterations, which influence tumor growth and invasiveness, with some alterations (eg, EGFR and ALK) conferring a better prognosis." (PMID 40537184, 2025). "Another RTK, epidermal growth factor receptor (EGFR), is frequently overexpressed in PDAC and is associated with tumor aggressiveness and postoperative recurrence." (PMID 40619414, 2025). "Since HER2 lacks a known ligand, EGF helps to simulate EGFR stimulation in vivo within the tumor microenvironment and aiding in the study of Wnt pathway’s interaction with HER2." (PMID 40642068, 2025). "We showed that EUDAL is a key determinant of the tumor cell response to hypoxia-induced EGFR activation." (PMID 40940319, 2025). "In CC models, curcumin significantly reduces the expression of VEGF, COX-2, and EGFR, thereby inhibiting tumor growth and angiogenesis." (PMID 41515171, 2025). "And compared with EGFR wild‐type (EGFRwt) tumors, EGFR mutant (EGFRmut) tumors are more heterogeneous, characterized tumor microenvironment (TME) and multiple tumor‐intrinsic factors." (PMID 40859900, 2025). "Tumor cells can develop resistance to EGFR inhibitors through various mechanisms, including the acquisition of secondary mutations in the EGFR gene." (PMID 39940134, 2025). "We examined in vitro expansion, cytokine secretion, killing activity against the three ESCC cell lines with different EGFR expression levels, and in vivo tumor control in a xenograft model." (PMID 40722671, 2025). "In the TME, hyperactivation of the EGFR/NF‐κB pathway increases tumour cell resistance to radiation, thereby reducing the efficacy of radiotherapy." (PMID 40830825, 2025). "This study shows that inhibiting the function of the tetra-transmembrane protein CMTM4 can sensitize tumor cells to EGFR inhibition and restrict tumor growth by repressing tumor inflammation." (PMID 39948411, 2025). "In summary, our epigenetic analysis not only identifies a significant demethylation of the EGFR promoter in pLN+ OSCC but also highlights the enrichment of pathways critical for tumour progression based on methylated regions." (PMID 40038875, 2025). "The focus is on their time-dependent effects on key regulatory proteins involved in tumor progression, including epidermal growth factor receptor (EGFR) for proliferation, vascular endothelial growth factor (VEGF) for angiogenesis, and caspase-3 for apoptosis." (PMID 40416168, 2025). "Chimeric antigen receptor (CAR) T-cell therapy targets proteins like EGFR, though challenges like tumor antigen heterogeneity and T-cell exhaustion remain." (PMID 40075700, 2025). "EGFR-activating alterations between both tumor types differ in their ligand dependence, meaning that the effect of EGFR ligands in GBM should receive more attention in follow-up studies." (PMID 39959305, 2025).
tumor (continued). "We conducted an in silico analysis using databases like The Cancer Genome Atlas, Gene Expression Omnibus, and Clinical Proteomic Tumor Analysis Consortium, along with immunohistochemistry staining, to study EGFR and Mcl-1 expression in HNCs." (PMID 38888847, 2025). "GBM is marked by genetic alterations, including EGFR amplification, PDGFRA mutations and IDH1/2 mutations, which drive tumor development and contribute to treatment resistance." (PMID 39781344, 2025). "In CRC, for example, inflammation-driven EGFR activation is associated with SPINK 1 overexpression, contributing to enhanced tumor proliferation and chemoresistance." (PMID 40872585, 2025). "Studies using different antibodies against EGFR and other tumor targets, to generate targeted hexavalent scTRAIL fusion proteins, will shed further light on the relevance of targeting on TRAIL’s antitumoral activity." (PMID 40328809, 2025). "The relative expression level of all four members of the HER family (wt-EGFR, HER2, HER3, and HER4), as well as the mutant type of EGFR (EGFRvIII) proteins, were examined in the tumour specimens from these patients by immunohistochemistry." (PMID 40227788, 2025). "Previous studies identified a correlation between high CD73 and increased PD-L1 expression, either in smaller cohorts of 15 to 25 EGFR tumours or in cohorts analysed after TKI treatment." (PMID 40149368, 2025). "This pathway has been identified as a crucial component of the mechanism of resistance to EGFR-TKIs and plays a part in tumor progression and immune responses." (PMID 40224214, 2025). "A univariate analysis indicated that the age, tumor size, nodal status, and EGFR score significantly influenced both 5-year DFS and OS." (PMID 40150035, 2025). "There is evidence that EGFR overexpression is reduced in metastatic TNBC cells compared to the primary tumor, and most trials involved advanced or metastatic TNBC." (PMID 40003864, 2025). "In tumor cells, EGFR tyrosine kinases are activated by various mechanisms, including mutation, overexpression, and autocrine or paracrine production of EGF family ligands." (PMID 40517166, 2025). "EGFR-BATs, comprising T cells coated with cetuximab and OKT3 bispecific antibodies, target tumor cells expressing EGFR, potentially leveraging the immune system to eradicate these cells." (PMID 40895848, 2025). "Investigation of the poor prognosis subtype 6 tissues revealed expression of CD44 and EGFR in ER+ tumor cells." (PMID 39808504, 2025). "Combined treatmentwith ActD and Dox reduced the expression levels of EGFR, pERK, andKi67 in the tumor tissues." (PMID 40032551, 2025). "In our study, we found that combining a JAK1 inhibitor with EGFR‐TKIs treatment enhances tumour control." (PMID 40162549, 2025). "In parallel, NCT04976218 specifies a phase I trial to evaluate CAR-EGFR-TGFR-KO T cells engineered through CRISPR/Cas9 to target TGF-β receptor II in previously treated EGFR-positive tumor cells." (PMID 40548119, 2025). "Sequential tissue sections from biopsy samples were stained for CEA, EpCAM, c-MET, and EGFR, with tumor expression levels quantified using the H-score method." (PMID 40563608, 2025). "For instance, what is the exact relationship between changes in EGFR expression levels and alterations in the immune characteristics of the tumor microenvironment?" (PMID 40819076, 2025). "The hydrogel can sustainably release prochlorperazine at the tumor site, which led to the increased expression of EGFR on the cell membrane, and thus enhances antibody‐dependent cell‐mediated cytotoxicity of cetuximab." (PMID 39560161, 2025). "Despite abundant genomic alterations in UASCC that are shared with other tumor types for which targeted therapies have been successfully developed, Cetuximab, an anti-EGFR antibody, remains the only approved gene-targeting drug for UASCC." (PMID 39896470, 2025).
tumor (continued). "Prolonged IL-10’s half-life and well-tolerated.Targeted EGFR-positive tumors.Improved tumor-specific cytotoxic activity of CD8+ T cells.Hindered DC-mediated apoptosis of CD8+ TILs.Overcame resistance to ICIs therapy." (PMID 40149345, 2025). "Strategies to mitigate this risk include targeting more tumor-specific epitopes, such as EGFR variant III, or engineering low-affinity CARs that preferentially bind to tumor cells exhibiting high antigen density." (PMID 40904467, 2025). "While this mechanism is consistent with previous studies showing that activated NPM1 supports tumor cell proliferation, migration, and invasion, primarily via the EGFR/MAPK signaling pathway, the precise molecular underpinnings remain to be fully elucidated." (PMID 41145488, 2025). "Research indicates that EML4-ALK fusion proteins and EGFR activation can upregulate PD-L1 expression, promoting tumor immune evasion." (PMID 41487577, 2025). "Good tolerance and early anti-tumor activity (NCT04259450) were demonstrated in Phase I trials in patients with advanced solid tumors expressing epidermal growth factor receptor (EGFR)." (PMID 41179878, 2025). "We observed stronger anti‐luciferase stains in the tumor cells (EGFR stained) with the tLNPs compared to the isoLNPs cancer samples." (PMID 39736115, 2025). "These genes were predominantly enriched in well‐known tumor‐related pathways, such as the EGFR signaling pathway and the PI3K/AKT signaling pathway." (PMID 39921252, 2025). "The secreted soluble EGFR-LiTE successfully redirected T cells to bind EGFR on tumor cell surface, converting them into efficient tumor cell killers." (PMID 41341587, 2025). "EXO-mediated transfer of oncogenic EGFR can effectively disrupt tight junctions and the integrity of ECs barriers, promoting tumor angiogenic sprouting." (PMID 40486870, 2025). "These cells recruited bystander T cells to target EGFR-positive tumor cells, overcoming the limitations of single-antigen CAR-T therapy." (PMID 40223940, 2025). "Liposomal nanohybrid cerasomes decorated with anti-EGFR mAb and PD-L1 mAb were explored for targeted tumor imaging and photodynamic therapy (PDT)." (PMID 39940134, 2025). "While petosemtamab can bind independently to cells expressing only the LGR5 antigen, the ability to simultaneously bind EGFR can in principle facilitate enhanced avidity-driven binding to dual-target-expressing cells within a tumor." (PMID 40427162, 2025). "In our study, we found that CMTM4 can modulate the tumor immune microenvironment by promoting EGFR recycling to increase G-CSF and CCL-1 production, which recruit neutrophils and MDSC to induce an immune suppressive tumor microenvironment." (PMID 39948411, 2025). "B10-B11 selectively binds to tumor cells that co-express high levels of both EGFR and PD-L1, as demonstrated in MDA-MB-231 and MNNG-HOS cells." (PMID 41155373, 2025). "Key molecular alterations include EGFR amplification, TERT promoter mutations, and chromosome 7 gain/chromosome 10 loss, all of which contribute to tumor progression and treatment resistance." (PMID 40722305, 2025). "Module 4 supports tumor survival and migration via EGFR signaling and cell adhesion pathways, enabling tumor adaptation in low-androgen environments." (PMID 40165961, 2025). "EMB-01 (bafisontamab) is a bispecific EGFR/cMET-targeted antibody currently under evaluation in a first-in-human (FIH) phase I/II study in advanced neoplasms, including NSCLC." (PMID 40277763, 2025). "This study identified ASPM as a novel regulator of EGFR-TKI resistance in NSCLC, with dual roles in promoting tumor aggressiveness and stabilizing EGFR signaling." (PMID 40979592, 2025). "Targeting EGFR with tyrosine kinase inhibitors (TKIs) like gefitinib effectively blocks these signaling pathways, reducing tumor growth and increasing cancer cell sensitivity to chemotherapy." (PMID 40610494, 2025).
tumor (continued). "Erlotinib, an epidermal growth factor receptor (EGFR) inhibitor, blocks pathways critical to tumor survival and proliferation." (PMID 40336633, 2025). "The role of eccDNA in cancer has been extensively documented, especially its function in amplifying oncogenes such as MYC and EGFR, which contributes to tumor heterogeneity and drug resistance 37,66,187." (PMID 40521196, 2025). "AFM24 is designed as a tetravalent BsAb that binds to CD16A on NK cells and macrophages and EGFR on tumor cells to activate the innate immune system and induce ADCC and ADCP." (PMID 40565299, 2025). "We anticipate that Cy3‐AptEGFR@BPNSs can intuitively and dynamically monitor EGFR expression levels in tumours, providing a robust imaging framework to guide the adoption of treatments and improve prognosis." (PMID 40368641, 2025). "Both are DARPin-fused to distinct TAAs (HER2, EGFR, and EpCAM), so the cage and key must co-localise on the tumour cell surface." (PMID 41465327, 2025). "Too few individuals were treated with an EGFR-inhibitor in first line to allow for comparisons according to tumour location." (PMID 40437037, 2025). "While liquid biopsy represents a valuable tool for detecting EGFR resistance mechanisms, only a pathological examination of tumor rebiopsy can reliably identify phenotypic transformation, which strongly influences therapy assessment and prognosis." (PMID 41226501, 2025). "More recently, a French group reported increased tumor cell death in vitro and delayed tumor growth with prolonged lifespan in tumor-bearing mice after treatment with venetoclax, cetuximab (an EGFR inhibitor) and radiation." (PMID 39970625, 2025). "They confer poor prognosis and resistance to anti-EGFR-based treatments, but they can be effectively addressed with tumor-agnostic approved targeted inhibitors." (PMID 41154394, 2025). "Next, we tried to identify the factors by which EGFR-overexpressed tumor cells enhance the pro-angiogenic effects of their sEVs." (PMID 39816681, 2025). "Cetuximab is a monoclonal antibody targeting EGFR that inhibited tumor cell growth and promoted apoptosis by blocking the EGFR signaling pathway." (PMID 40959565, 2025). "We also found that CSS-H tumor samples demonstrated greater sensitivity to multiple inhibitors of the EGFR, PI3K, and ABL signaling pathways." (PMID 39822281, 2025). "Wild-type EGFR disruption suppressed HER2/HER3 expression, but mutant EGFR loss or TKI resistance increased HER2/HER3 expression, promoting tumor cell survival and drug resistance via cyclin D1." (PMID 39790707, 2025). "The epidermal growth factor receptor (EGFR) is a crucial regulator of epithelial cell behavior and tumor activity derived from epithelial cells." (PMID 40005958, 2025). "Concurrently, the capacity of immune cells to eliminate tumor cells within the TME of EGFR mutant LUAD was markedly diminished." (PMID 40130724, 2025). "Future studies should extend this work to incorporate primary tumor cells and additional subtypes, such as EGFR-mutant cells, to enhance the generalizability and robustness of the findings." (PMID 40432889, 2025). "can not only non‐invasively predict the expression of VEGF and EGFR, but also reflect tumor angiogenesis and cell proliferation." (PMID 39962757, 2025). "Pyrosequencing of the EGFR gene and Moffitt Illumina TruSight Tumor 26 (TST26) sequencing were performed at the MCC." (PMID 40076686, 2025). "TGF-α plays a crucial role in stimulating tumor growth and enhancing resistance to therapy by activating the EGFR pathway." (PMID 40596459, 2025). "Various tumor antigens—including VEGFR2, EGFR, HER2, MAGE, MUC1, FGFR, Flt4, and tumor-associated carbohydrate antigens—have been used in preclinical vaccine candidates." (PMID 40427029, 2025).
tumor (continued). "CIK stably transfected with this construct induced a synergistic cytotoxic activity in vitro against the TNC+EGFR+ MDA-MB-231 tumor target, compared to either CIK carrying the sBiTE or CAR-TNC5 alone." (PMID 40944718, 2025). "As an example, in EGFR-TKI resistant tumors, tumor-associated macrophages (TAMs) undergo significant polarization, transitioning from the pro-inflammatory M1 phenotype to the immunosuppressive M2 phenotype." (PMID 40003951, 2025). "Given prior studies implicating USP8 in EGFR ubiquitination, we evaluated EGFR immunoprecipitation following corticotroph tumor EGF-treatment." (PMID 40386408, 2025). "This targeted delivery system resulted in significant tumor growth inhibition in a mouse model of EGFR+ cancer, suggesting that PD-L1 targeting in TAMs offers a promising therapeutic strategy for enhancing ICB efficacy." (PMID 40317075, 2025). "H-scores of CEA, EpCAM, c-MET, and EGFR were compared between tumor and adjacent normal epithelial tissues using pre- and post-treatment specimens." (PMID 40563608, 2025). "Despite the fact that TKIs inhibit signaling pathways that control genes, key signaling pathways in tumor cells can still be permanently activated through bypass mechanisms such as MET or EGFR gene amplification, and AXL activation." (PMID 40574095, 2025). "Its pathophysiology implicates tumor-secreted peptides—notably transforming growth factor alpha (TGF-α)—that stimulate epidermal hyperplasia via epidermal growth factor receptor (EGFR) activation." (PMID 41357602, 2025). "Due to EGFR's role in the regulation of RhoC during tumor cell migration and invasion, RhoC GTPase was selected for further study." (PMID 40754248, 2025). "EGFR-mutant NSCLC exhibited distinctive TME features in PD-L1 expression, tumor mutation burden (TMB), and CD8+ tumor infiltration lymphocytes (TILs) compared with wild type NSCLC." (PMID 40002895, 2025). "Regarding known tumor drivers in NSCLC and response to ICB, there are some data where tumors driven by EGFR variants and ALK rearrangement have been shown to be resistant to ICB regardless of PD-L1 expression status." (PMID 40011914, 2025). "Two patients with EGFR-mutated and ALK-rearranged tumor had received tyrosine kinase inhibitors previously." (PMID 39850629, 2025). "EGF is one of the ligands of EGFR, and its binding to EGFR activates downstream signaling pathways that promote tumor cell proliferation and survival." (PMID 40859900, 2025). "Target-modification strategies such as ligand conjugation with CD44 or EGFR can further improve tumor selectivity and therapeutic efficiency." (PMID 40943340, 2025). "These cells often show high ten-eleven translocation (TET) enzyme expression, leading to DNA demethylation in key regulatory regions, including RTKs (e.g., EGFR), tumor suppressors (e.g., PTEN, DIAPH3), and oncogenes (e.g., AKT, BRAF)." (PMID 40358199, 2025). "In cases with EGFR mutations, Univariate COX regression analysis revealed that tumor pathologic grade, proximal metastases, HLF expression, and the number of CTCs were correlated with progression-free survival." (PMID 40124619, 2025). "ICOS expression was also significantly linked with higher tumor grade (P = 1.59e−3), WHO histological subtype (P = 1.49e−3) and the presence of EGFR mutations (P = 4.67e−8)." (PMID 39378431, 2025). "It has been widely used to detect druggable tumor-specific genes such as EGFR, ALK, ROS1, BRAF, KRAS, NTRK1/2/3, ERBB2, RET, and MET in patients with NSCLC." (PMID 41515905, 2025). "the co‐injection of 3T3 Cxcl14‐OE cells with human EGFR‐mutant LUAD cells exhibited tumour proliferation and drug resistance of gefitinib and osimertinib in vivo." (PMID 40162549, 2025). "To explore this, we selected TAVO412, a novel EGFR × cMet × VEGF trispecific antibody known for its potent tumor growth inhibition across multiple solid tumors." (PMID 41228205, 2025).